CGA (glycoprotein hormones, alpha polypeptide)
Diseases named in the same sentence as CGA in open-access papers (continued):
Sharing a sentence is not in itself a finding about the gene and the disease.
breast carcinoma (13 papers, 2014 to 2025). "In contrast, tumors with an hPRLrIlo/hPRLrLhi ratio were enriched in genes associated with luminal breast cancer (e.g., CGA, PVALB, NOVA1), and were more likely to be small in size and early stage." (PMID 33772010, 2021). "It has previously been associated with prevalent breast cancer, incident COPD, an age-by-sex interaction and the levels of 17 proteins including CRP, SERPING1, CHAD and CGA." (PMID 41361833, 2025). "The advent of the IHC technique makes it possible to identify the neuroendocrine phenotypes in breast cancer subpopulations by displaying their immunoreactivity to CgA, Syn, neuron-specific enolase (NSE), and CD56, which are usually negative in IBC-NSTs." (PMID 35692784, 2022). "CGA is also considered as a novel estrogen receptor response gene in breast cancer and an outstanding candidate marker for predicting response to endocrine therapy." (PMID 33858365, 2021). "CgA, Syn, NSE, and CD56 were neuroendocrine differentiation markers for breast carcinoma with neuroendocrine features." (PMID 36836889, 2023). "Malignant melanoma expressed HMB45, MelanA, and S-100; small cell lung cancer expressed TTF-1, CD56, and CgA; hepatocellular carcinoma expressed GPC-3, hepatocyte, and Sall4; breast cancer expressed ER, PR, Her-2, and GCDFP-15." (PMID 37608278, 2023). "Four known biomarkers (CHEK2 in both plasma and urine, CDKN1B, PCNA, and THBS1) were identified as false positives (red) in our breast cancer list, and seven (KRAS, GDNF in both breastmilk and plasma, MYCL1 in both blood and serum, CD40LG, CGA, CTAG1A, ERCC6, and HRAS) in our lung cancer list." (PMID 25379168, 2014). "However, elevated CgA levels have also been observed in some non-GEP-NENs, including lung cancer, breast cancer, and prostate cancer." (PMID 39895797, 2025).
paraganglioma (13 papers, 2014 to 2025). A benign or malignant neoplasm arising from paraganglia located along the sympathetic or parasympathetic nerves. "Interestingly, all the tumors with a SDHB or SDHD mutation in our series corresponded to paragangliomas and, in this subgroup of patients, combined measurement of CgA, WE-14 and EM66 also provided 100% sensitivity." (PMID 24523932, 2014). "Immunohistochemical analysis confirmed paraganglioma (CgA+, S100+, Ki‐67 proliferation index 20%, CK8/18−)." (PMID 40587311, 2025). "Surgical laparoscopic resection removed a solitary 4.0 × 3.5 cm mass near the abdominal aorta, with histopathology confirming paraganglioma (CgA+, S100+, Ki‐67: 20%, CK 8/18−)." (PMID 40587311, 2025). "A positive staining with synaptophysin, NSE, CD56, NSE, Syn, CgA and S-100 was observed in the present case, which was compatible with paraganglioma." (PMID 24520306, 2014). "In fact, the combination of WE-14 with either CgA or EM66 test assays achieved 100% sensitivity for the diagnosis of paragangliomas and sporadic or malignant pheochromocytomas if taken separately to account for the heterogeneity of the tumor." (PMID 24523932, 2014). "However, the elevated serum CgA was rarely present in subjects with pituitary adenomas (13%), insulinomas (10%), and paragangliomas (8%)." (PMID 32020844, 2020). "The accurate diagnosis of paraganglioma could be based on immunohistochemical staining of syn, cgA, Ki-67, S100, and PCK." (PMID 29979384, 2018). "Furthermore, the absent expression of high and low molecular weight Cytokeratins did not support the hypothesis of a metastatic renal cell carcinoma and the CgA negativity was against the supposition of a paraganglioma." (PMID 26925281, 2016). "The histopathological examination showed positive staining for NSE, Syn, CgA and CD56, sustentacular cells stained positive for S-100 and the Ki-67 staining revealed a proliferation index of <2%, compatible with paraganglioma." (PMID 24520306, 2014). "Moreover, 100% sensitivity was reached when WE-14 and CgA tests were combined for the diagnosis of sporadic or malignant tumors, and when WE-14 and EM66 tests were used for the diagnosis of paragangliomas." (PMID 24523932, 2014). "Immunohistochemical findings for paragangliomas are as follows: S-100 positivity; positivity for neuroendocrine markers such as NSE, CgA and Syn but not MyoD1, Des or others; and PAS positivity without positive cytoplasmic particles." (PMID 38291475, 2024).
lymph node metastasis (12 papers, 2012 to 2025). "Results showed that stage, stromal invasion, lymph vascular space invasion, lymph node metastasis, cervical–uterine junction invasion and CgA were confirmed as independent risk factors of cancer recurrence." (PMID 36769874, 2023). "By comparing G-NET patients with or without LNM, we found that older age, preoperative lower albumin level, higher CEA level, higher INR, longer TT, higher Ki67, and CgA positive rate were associated with lymph node metastasis." (PMID 33789664, 2021). "Univariate Cox regression analysis showed that FIGO stage (P<0.001), tumor mass size (P<0.001), lymph node metastasis (P<0.001), depth of stromal invasion (P = 0.022), and CgA stained positive (P = 0.034) were associated with prognostic of patients with SCCC." (PMID 22529895, 2012). "Several studies have investigated prognostic factors, identifying some unfavorable markers for survival, such as high plasma CgA levels, the presence of liver or lymph node metastases, CHD, tumor size, histological grade of differentiation, and elderly age." (PMID 37627093, 2023). "Through bioinformatic analysis, we found that chromogranin A (CgA) was positively correlated with invasion and lymph node metastasis." (PMID 36899368, 2023). "The expression of CgA was positively correlated with the depth of invasion (P = 0.01) and lymph node metastasis (P = 0.03)." (PMID 36899368, 2023). "At the same time, tumour size, location, lymphovascular invasion, muscularis propria invasion, Ki 67 index, CgA and lymph node metastasis were important prognostic factors." (PMID 34997303, 2022). "have shown that the CgA levels were significantly higher in GEP-NET patients with more than five liver metastases than those with fewer than five liver metastases or lymph node metastases." (PMID 34868938, 2021). "The sensitivity of an elevated CgA concentration was 50% in cases with localized disease, 80% in cases with local lymph node metastases and 100% in cases with distant metastases." (PMID 33138020, 2020). "The current standards for lymph node metastasis detection are histological examination after Hematoxylin and Eosin (H&E) and CgA immunohistochemical (IHC) staining." (PMID 22720672, 2012). "However, factors with p < 0.05 including stage, stromal invasion, nerve invasion, lymph vascular space invasion, lymph node metastasis, cervical–uterine junction invasion and CgA were further analyzed using multivariate regression analysis." (PMID 36769874, 2023). "We hypothesized that a PCR-based approach for CgA detection would be more sensitive than either H&E or CgA IHC for detecting lymph node metastases." (PMID 22720672, 2012).
chronic atrophic gastritis (10 papers, 2016 to 2024). Atrophic gastritis that is persistent and long-standing. "It should be noted that CgA levels can be influenced by various conditions such as gastritis and liver cirrhosis, limiting its use as a tumor marker despite its correlation with tumor progression in several studies." (PMID 38038419, 2023). "Moreover, an advantage over blood CgA is the reliability of results, which are not affected by gastritis or proton pump inhibitor intake." (PMID 39409968, 2024). "Unlike CgA, factors such as PPI treatment and gastritis have no bearing on the results." (PMID 36233409, 2022).
gastrinoma (9 papers, 2014 to 2023). "In Case 3 gastrinoma, tumor cells were granular, less stained for gastrin but strongly stained for CgA and weakly for SPY." (PMID 32020844, 2020). "CgA showed an acceptable sensitivity only for well-differentiated NENs and may predict disease progression, especially in advanced NENs and gastrinomas." (PMID 37685358, 2023). "A high sensitivity of CgA in gastrinoma makes it useful for a post-treatment follow-up." (PMID 36233409, 2022). "Similarly, the application of proton pump inhibitors, which is the symptomatic treatment of choice in patients with gastrinoma, increases plasma levels of CgA." (PMID 29232390, 2017). "Some of non-insulinoma PNETs with relatively small size still had very high serum levels of CgA, for example, CgA level was 4572 ng/ml in a gastrinoma of 1.5 cm in size, and the highest CgA level in present study was more than 9000 ng/ml in a glucagonoma of 2.5 cm in size." (PMID 25099181, 2014). "The other functioning Pan-NETs including gastrinomas and glucagonomas are also more strongly positive for SPY than CgA, suggesting active SV involvement on the early gastrin and glucagon section, respectively." (PMID 32020844, 2020). "However, there is rising evidence that the tumor localization may determine the total amount of serum levels of CgA, as patients with Zollinger Ellison Syndrome (gastrinoma) show much higher levels of plasma CgA compared to patients with GEP-NEN of the small bowel." (PMID 29232390, 2017). "However, it is worth noting that the characteristics of hematoxylin and eosin (H&E) staining with gastrinoma and solid pseudopapillary tumors are similar and may be confused, even when specific typical immunohistochemical indicators, such as Syn or CgA, are observed." (PMID 24932294, 2014). "Among Pan-NETs, insulinomas were weaker stained for CgA than the non-β-cell tumors, including gastrinomas, glucagonomas, pancreatic polypeptidomas, and non-functioning Pan-NETs, and these non-β-cell Pan-NETs are more aggressive than insulinomas." (PMID 33485291, 2021). "Similar to previous studies, we found that CgA levels in patients with gastrinomas were much higher than those in patients without gastrin-secreting PNETs." (PMID 25099181, 2014). "In addition, one report showed that in 9 of the 10 patients with gastrinoma, CgA values were raised, even in the absence of metastasis." (PMID 25099181, 2014).
irritable bowel syndrome (9 papers, 2008 to 2025). Irritable bowel syndrome (IBS) is a chronic functional condition of the lower gastrointestinal (GI) tract characterized by abdominal pain or discomfort and disordered bowel habit (diarrhea, constipation, or fluctuation between the two). "CgA’s ability to negatively affect the growth of certain pathogenic/opportunistic bacteria may play a role e.g. in the complex pathophysiology of irritable bowel syndrome (IBS)." (PMID 40370467, 2025). "In a previous study, chromogranin A (CgA) cell density in the colon of patients with irritable bowel syndrome (IBS) was found to be reduced." (PMID 22992886, 2012). "Moreover, even if increased duodenal CgA-producing cells are found in the duodenum of patients with irritable bowel syndrome, plasma CgA levels are normal." (PMID 34064688, 2021). "Chromogranin A (CgA) is a common marker for the gastrointestinal endocrine cells, and it is abnormal in irritable bowel syndrome (IBS) patients." (PMID 25918524, 2015). "In a previous study, the density of CgA-secreting cells was observed to be abnormal in the stomach of patients with irritable bowel syndrome (IBS)." (PMID 25174455, 2014). "The density of duodenal CgA cells is reduced in patients with irritable bowel syndrome (IBS)." (PMID 25028588, 2014). "Psychophysiological processing has been reported to play a crucial role in irritable bowel syndrome (IBS) but there has been no report on modulation of the stress marker chromogranin A (CgA) resulting from muscle stretching." (PMID 18983682, 2008).
melanoma (8 papers, 2012 to 2026). A malignant, usually aggressive tumor composed of atypical, neoplastic melanocytes. "Catestatin (CST), a Chromogranin A (CgA)–derived peptide with immunomodulatory and reparative properties, has been implicated in tissue protection, but its role in melanoma remains unknown." (PMID 41279995, 2025). "The expression and role of CST, a Chromogranin A (CgA)-derived peptide with immunomodulatory and reparative properties in skin injury led us to examine its connection to melanoma." (PMID 41646326, 2026). "Malignant melanoma expressed HMB45, MelanA, and S-100; small cell lung cancer expressed TTF-1, CD56, and CgA; hepatocellular carcinoma expressed GPC-3, hepatocyte, and Sall4." (PMID 37608278, 2023). "To investigate the expression frequency of CgA, Syn, and CD56, we enrolled 308 melanoma specimens, including 84 (27.3%) biopsies." (PMID 34454530, 2021). "We retrospectively analyzed the expression of chromogranin A (CgA), synaptophysin (Syn) and CD56 as neuroendocrine markers in 308 cases with melanomas." (PMID 34454530, 2021). "In previous studies we have shown that low concentrations of CgA can reduce the trans-endothelial migration of other malignant cells, such as TSA mammary adenocarcinoma and B16 melanoma cells, by enhancing endothelial VE-cadherin dependent adherence junctions." (PMID 27203389, 2016). "In our two cases, immunohistochemical staining demonstrated that the tumor cells expressed HMB45, S-100, pan melanoma and Vimentin, and did not express CK, EMA, CgA, Syn, HCG, HMW-CK, Desmin, SM-actin, TTF-1, and SCLC." (PMID 22992473, 2012).
neuroblastoma (8 papers, 2003 to 2022). Neuroblastoma (NB) is the most common solid, extracranial childhood tumor. "The TMA also included information on tumor grade, cluster of differentiation 56 (CD56) staining, and chromogranin A (CgA), which are diagnostic markers for neuroblastoma." (PMID 36185250, 2022). "In particular, we observed a significant increase of Chromogranin A (CgA) mRNA expression levels, a neuroendocrine secretory protein, which is a useful prognostic and diagnostic tool for neuroblastoma and correlates with tumor burden and survival patients’." (PMID 29930753, 2018). "As further evidence of our observed phenotypic change, following CgA knockdown in neuroblastoma cells, we also performed rescue experiment to restore CgA expression." (PMID 30833285, 2019). "CgA is a tissue specific protein restricted to the diffuse neuroendocrine system, and widely expressed in neuroblastomas." (PMID 30833285, 2019). "In an in vivo xenograft neuroblastoma model, CgA knockdown led to increased S-phenotypic marker expression at both protein and mRNA levels." (PMID 30833285, 2019). "Human neuroblastoma SH-SY5Y cells stably transfected with shRNA CgA or nonsense control were subcutaneously inoculated into five-week-old male athymic nude mice at the density of 1×106 cells/animal." (PMID 30833285, 2019). "Rescue re-expression of CgA in the shRNA CgA neuroblastoma cells resulted in increased BrdU incorporation (vector versus CgA rescue, 1.1±0.1 versus 2.1±0.05, P<0.05)." (PMID 30833285, 2019). "In vitro studies have demonstrated alterations in CgA transcription during neuroblastoma differentiation induced by retinoic acid and cAMP." (PMID 30833285, 2019). "Collectively, these results supported our initial findings in SH-SY5Y cells and confirmed the effects of CgA in cell proliferation and differentiation in neuroblastoma." (PMID 30833285, 2019). "In summary, we demonstrated that depletion of CgA in neuroblastoma inhibits cell proliferation and leads to Schwannian differentiation in vitro." (PMID 30833285, 2019). "To elucidate the biological function of CgA in modulation of neuroblastoma proliferation and differentiation, we used a short hairpin RNA (shRNA)-directed knockdown approach to deplete CgA expression in neuroblastoma SH-SY5Y cells in vitro." (PMID 30833285, 2019). "Confirming prior studies in other tumor types, we observed reduced AKT/ERK activation following CgA knockdown in neuroblastoma cells." (PMID 30833285, 2019). "This in turn leads to increased sensitivity to the anti-proliferative effect of chemical inhibitor that we observed in the shRNA CgA knockdown neuroblastoma cells." (PMID 30833285, 2019). "These knockout studies corroborated our prior findings using shRNA and demonstrated that reducing CgA expression in neuroblastoma SH-SY5Y cells inhibits in vitro cell proliferation and promotes cell differentiation toward a Schwannian cell phenotype." (PMID 30833285, 2019). "Serum CgA levels in neuroblastoma patients correlate with tumor burden and can be used as a sensitive and specific diagnostic and prognostic disease marker." (PMID 30833285, 2019). "Biochemical analysis evidenced a decrease of neuronal biomarkers expression and a significant increase of TH, DBH, NSE and CgA, indexes of neuroendocrine differentiation and considered unfavorable prognostic neuroblastoma biomarkers." (PMID 29930753, 2018). "To confirm this observation, we studied the expression of Id2 and CgA markers, which are respectively induced and downregulated during hypoxia-mediated neuroblastoma dedifferentiation." (PMID 17655754, 2007). "We next tested effects of CgA depletion in neuroblastoma tumor growth in vivo." (PMID 30833285, 2019). "We observed that whereas atRA treatment caused obvious neurite outgrowth in nonsense control neuroblastoma cells as previously reported, treatment of the shRNA CgA transfectants with atRA (20 μM) did not change the S-type morphology." (PMID 30833285, 2019).
neuroblastoma (continued). "Expression of GFAP was reduced (nonsense versus shRNA CgA, 1.0±0.1 versus 0.02±0.01, P<0.05), whereas expression of PMP22 (1.0±0.02 versus 3.3±0.5, P<0.05) and SERPINF1 (1.0±0.1 versus 3.1±0.5, P<0.01) was increased in the shRNA CgA transfectants compared to nonsense control neuroblastoma cells." (PMID 30833285, 2019). "However, given the striking alterations we observed of CgA depletion in vitro with a marked phenotypic shift, we still feel that our findings are significant and could enable novel therapeutic approaches in neuroblastoma differentiation therapy." (PMID 30833285, 2019). "However, the potential role, if any, for CgA itself in regulating neuroblastoma proliferation and/or differentiation remains unclear." (PMID 30833285, 2019). "To further support a role for altered autocrine IGF-II proliferative actions following CgA depletion, we performed a ‘rescue’ experiment by treating both shRNA CgA and nonsense control SH-SY5Y neuroblastoma cells with exogenous IGF-II." (PMID 30833285, 2019). "Together these results suggest that CgA maintains IGF secretion and intracellular signaling to regulate proliferation and differentiation in neuroblastomas." (PMID 30833285, 2019). "To further support our findings on the actions of CgA to alter neuroblastoma phenotype and proliferation rates in vitro, we also used CRISPR-Cas9 to completely deplete CgA expression in the SH-SY5Y cells." (PMID 30833285, 2019). "Prior studies have demonstrated reduced CgA transcription following atRA and 12-O-tetradecanoylphorbol-13-acetate (TPA)-induced neuroblastoma neuronal differentiation, concomitant with growth arrest." (PMID 30833285, 2019). "Although we did observe reduced tumor growth in vivo in the shRNA CgA knockdown neuroblastoma cells, this did not attain statistical significance." (PMID 30833285, 2019). "The mice inoculated with SH-SY5Y shRNA CgA developed tumors later than the mice inoculated with nonsense control neuroblastoma cells." (PMID 30833285, 2019). "The biochemical differentiation profile of neuroblastoma cells overexpressing TMODs showed a significant increase of MAP2 and GAP43, mimicking then the “neuronal differentiation” obtained by retinoic acid, and an overall decrease of TH, DBH and CgA mRNA expression levels." (PMID 29930753, 2018).